EFHB (EF-hand domain family member B)
Description:
Microtubule inner protein (MIP) part of the dynein-decorated doublet microtubules (DMTs) in cilia axoneme, which is required for motile cilia beating. Cytosolic sensor for calcium, modulates the interaction of STIM1 and ORAI1 upon store depletion and the activation of store-operated Ca(2+) entry (SOCE) and NFAT translocation from cytosol to nucleus.
Synonyms: CFAP21; FLJ25200
Tractability: Small molecule: a structure with a bound ligand is known.
Gene: Protein-coding gene on chromosome 3 (19,879,472 to 19,947,025, reverse strand). Ensembl gene ENSG00000163576.
Subcellular location: Cytoplasm, cytoskeleton, cilium axoneme; Cytoplasm, cytoskeleton, flagellum axoneme; Cytoplasm
Subcellular location (Human Protein Atlas): Cytosol; Connecting piece; Nuclear bodies; Vesicles
Gene Ontology:
Molecular function: calcium ion sensor activity; protein binding; calcium ion binding
Biological process: negative regulation of protein binding; regulation of calcineurin-NFAT signaling cascade; regulation of store-operated calcium entry; flagellated sperm motility
Cellular component: axonemal microtubule; axonemal A tubule inner sheath; sperm flagellum; axoneme; cytoplasm
Genetic constraint (gnomAD): Loss-of-function variants: 76 observed, 73.92 expected, observed/expected ratio (o/e) 1.03, 90% interval 0.85 to 1.24. The upper end of that interval is the gene's LOEUF score, 1.24, which puts it in group 5 of 6, group 1 being the genes least tolerant of losing a copy. Missense variants: 988 observed, 942.64 expected, observed/expected ratio (o/e) 1.05, 90% interval 0.99 to 1.11. Synonymous variants: 301 observed, 319.83 expected, observed/expected ratio (o/e) 0.94, 90% interval 0.86 to 1.03.
Homologues: Orthologues: chimpanzee EFHB (99% identical), macaque EFHB (91% identical), dog EFHB (79% identical), pig EFHB (77% identical), rabbit EFHB (76% identical), mouse Efhb (69% identical), rat Efhb (68% identical), guinea pig EFHB (67% identical), zebrafish efhb (34% identical), tropical clawed frog efhb (32% identical), Caenorhabditis elegans efhc-1 (5% identical). Paralogues in human: EFHC2 (13% identical), EFHC1 (11% identical).
Diseases named in the same sentence as EFHB in open-access papers:
EFHB is named in the same sentence as 7 diseases in open-access papers, as found by Europe PMC text mining. Sharing a sentence is not in itself a finding about the gene and the disease. The quoted sentences say what the papers report.
breast carcinoma (1 paper, 2021). "Here, we show that the expression and/or function of SARAF and EFHB is altered in breast cancer cells and both proteins are required for cell proliferation, migration, and viability." (PMID 34439314, 2021). "In aggregate, SARAF and EFHB are required for the fine modulation of SOCE in breast cancer cells and play an important role in the maintenance of proliferation, migration, and viability in these cells." (PMID 34439314, 2021). "Our results indicate that SARAF and EFHB are expressed in breast cancer and pre-neoplastic breast epithelial cells and play a relevant role in SOCE." (PMID 34439314, 2021). "Here, we show that SARAF and EFHB are expressed in neoplastic and pre-neoplastic breast cells, with breast cancer cells showing upregulation of EFHB expression." (PMID 34439314, 2021). "Finally, we used a combination of approaches to show that molecular knockdown of SARAF and EFHB significantly attenuates the ability of breast cancer cells to proliferate and migrate, as well as cell viability." (PMID 34439314, 2021). "While SARAF expression is similar in neoplastic and pre-neoplastic cells, EFHB is overexpressed in breast cancer cells, which might partially explain the enhanced SOCE observed in cancer cells." (PMID 34439314, 2021). "However, while the expression of SARAF is similar in breast cancer and pre-neoplastic cells, EFHB expression is significantly greater in cancer cells." (PMID 34439314, 2021). "Cell viability, proliferation, and migration is strongly dependent on SARAF and EFHB, or exclusively SARAF, in breast cancer and pre-neoplastic cells, respectively, thus suggesting that these proteins play an important role in breast cancer development and progression." (PMID 34439314, 2021). "Our results further indicate that EFHB and SARAF are required for breast cancer MCF7 and MDA-MB-231 cells viability, proliferation, and migration, although the signaling pathway might differ between both cell types." (PMID 34439314, 2021).
glioma (1 paper, 2022). A benign or malignant brain and spinal cord tumor that arises from glial cells (astrocytes, oligodendrocytes, ependymal cells). "EFHB, which is depicted in brown, is primarily involved in DNA metabolism and chromatin remodeling in gliomas." (PMID 35769464, 2022). "Similarly, we found that the coexpression subnetwork of EFHB in glioma regulates DNA metabolism and chromatin remodeling of tumor cells." (PMID 35769464, 2022).
Stroke (1 paper, 2023). Sudden impairment of blood flow to a part of the brain due to occlusion or rupture of an artery to the brain. "Herein, EFHB resulted in being upregulated, so we can hypothesize that it could have a role in regulating correct neuronal activity during post-stroke recovery." (PMID 37508918, 2023).
triple-negative breast carcinoma (1 paper, 2021). An invasive breast carcinoma which is negative for expression of estrogen receptor (ER), progesterone receptor (PR), and human epidermal growth factor receptor 2 (HER2). "EFHB expression is upregulated in luminal and triple negative breast cancer (TNBC) cells and is essential for full SOCE in these cells." (PMID 34439314, 2021). "In the present study, we have investigated the role of SARAF and EFHB in SOCE in ER+ and triple negative breast cancer (TNBC) cells." (PMID 34439314, 2021).
EFHB also shares sentences with these, for which no sentence is quoted: asthenozoospermia (1 paper); cancer (1); tumor (1).